MID1 (midline 1)
Diseases named in the same sentence as MID1 in open-access papers (continued):
Sharing a sentence is not in itself a finding about the gene and the disease.
tumor (6 papers, 2014 to 2024). "One of its most interesting targets with the aim of unraveling tumor biology is the microtubule-associated ubiquitin E3 ligase MID1, whose downregulation in human solid tumors has been associated with a more aggressive phenotype and with an increased invasiveness." (PMID 26880947, 2016). "MDSC-Exo-upregulated circMID1 and MID1 expressions were inhibited by si-circMID1 in tumor tissues, while downregulated miR-506-3p expression was increased by si-circMID1." (PMID 35918733, 2022). "Mechanistically, MDSC-derived exosomal S100A9 increased circMID1 expression to sponge miR-506-3p, leading to increased MID1 expression and accelerated tumor progression." (PMID 35918733, 2022). "The anti-tumour functions of PP2A and associated mRNAs suggest a regulatory role of the MID1 complex in cancer as well." (PMID 24484909, 2014). "MID1, a negative regulator of the tumor-suppressor PP2A, is known to promote PI3K, mTOR, NFκB and Hh signaling." (PMID 24913494, 2014). "Mechanistically, we showed that MDSC-derived exosomal S100A9 increased circMID1 expression to sponge miR-506-3p, which might then lead to increased MID1 expression and accelerate tumor progression." (PMID 35918733, 2022). "Notably, high MID1 expression was especially correlated with a histological tumor pattern referred to as cribriform." (PMID 24913494, 2014). "Mechanistically, MDSC‐derived exosome S100A9 adsorbed miR‐506‐3p by upregulating circMID1 expression, leading to increased midline 1 (MID1) expression and accelerated tumor progression." (PMID 39239069, 2024).
infection (3 papers, 2014 to 2023). The state of being infected such as from the introduction of a foreign agent such as serum, vaccine, antigenic substance or organism. "In other human pathogenic fungi, such as C. albicans and C. neoformans, the virulence of CCH1 and MID1 null mutants was attenuated in the respective mouse infection models." (PMID 25083783, 2014).
neurodegenerative disease (3 papers, 2018 to 2021). A disorder of the central nervous system characterized by gradual and progressive loss of neural tissue and neurologic function. "With respect to neurodegenerative diseases, one important aspect of MID1 function is its ability to bind to mRNA and induce translation." (PMID 34659371, 2021). "However, after the discovery that MID1 is responsible for OS, it took another decade until the first connection between MID1 and neurodegenerative diseases was found." (PMID 34659371, 2021). "However, several lines of evidence support a role for MIG12’s protein-protein interaction partner, MID1, in both neurodevelopmental disorders and neurodegenerative disease." (PMID 30357366, 2019).
inflammation (1 paper, 2022). Aberrant reaction of the microcirculation characterized by movement of fluid and leukocytes from the blood into extravascular tissues. "Targeting the Mid1-PP2Ac axis may be a useful way to reduce pathological lung inflammation in abdominal sepsis." (PMID 36614145, 2022).
MID1 also shares sentences with these, for which no sentence is quoted: Intellectual disability (4 papers); cleft lip (2); colorectal cancer (2); Diabetes (2); familial Mediterranean fever (2); genetic disease (2); herpes simplex encephalitis (2); pneumonia (2); acute promyelocytic leukemia (1); adenovirus infection (1); allergic rhinitis (1); atopic dermatitis (1); autism spectrum disorder (1); Autoimmunity (1); bladder cancer (1); cardiomyopathy (1); CHARGE syndrome (1); congenital heart disease (1); congenital heart malformations of (1); Cornelia de Lange syndrome 4 (1); COVID-19 (1); craniofrontonasal syndrome (1); encephalitis (1); fibrosis (1); glioblastoma (1); heart failure (1); hepatocellular carcinoma (1); hypertrophic cardiomyopathy (1); immune disorder (1); Kallmann syndrome (1).
A further 25 diseases each share a sentence with MID1 in 1 paper.